ATP8B1 (ATPase phospholipid transporting 8B1)
Diseases named in the same sentence as ATP8B1 in open-access papers (continued):
Sharing a sentence is not in itself a finding about the gene and the disease.
ATP8B1 also shares sentences with these, for which no sentence is quoted: cholera (23 papers); Alagille syndrome (2); biliary atresia (2); BRIC type 2 (2); Diarrhea (2); diarrheal disease (2); Failure to thrive (2); glycogen storage disease (2); liver cirrhosis (2); myotonic dystrophy (2); Pruritus (2); alpha 1-antitrypsin deficiency (1); Autoimmunity (1); bacterial infection (1); bile duct carcinoma (1); bile duct tumors (1); biliary cirrhosis (1); cholangiocarcinoma (1); cholelithiasis (1); cholestatic jaundice (1); coagulopathy (1); dyslipidemia (1); gastrointestinal disease (1); Hepatitis (1); hepatitis B (1); Hodgkins lymphoma (1); hyperlipidaemia (1); Hypoalbuminemia (1); hypothyroidism (1); intestinal cancer (1).
A further 25 diseases each share a sentence with ATP8B1 in 1 paper.